CD274 (CD274 molecule)
Diseases named in the same sentence as CD274 in open-access papers (continued):
Sharing a sentence is not in itself a finding about the gene and the disease.
tumor (continued). "The repression of AT3 tumor growth was accompanied by increases in STAT-1 signaling, the expression of STAT-1 target genes, such as Cxcl9 and Cd274, the recruitment of T cells, and the re-sensitization of otherwise resistant AT3 tumors to PD-1 immunotherapy." (PMID 37500611, 2023). "Here, by Cox modeling, we develop IRS—which combines TMB with CD274, PDCD1, ADAM12 and TOP2A quantitative expression—to predict pembrolizumab rwPFS (648 patients; 26 tumor types; IRS-High or -Low groups)." (PMID 36750617, 2023). "Programmed death-1 (PD-1) is an immunoinhibitory receptor expressed by T-cells and programmed death ligand 1 (PD-L1), also called CD274, is its ligand, being expressed in tumor cells." (PMID 36670786, 2023). "The major immune checkpoints include PDCD-1, CD274 (also known as PD-L1), CTLA-4, HAVCR2 (also called TIM-3), LAG-3 and TIGIT which are responsible for tumor immune escape." (PMID 37810780, 2023). "The proportion of CD274 + cells was relatively low, responding to the fact that PDAC is a cold tumor." (PMID 36944944, 2023). "PD-1, a type I transmembrane glycoprotein bound by glycoproteins PD-L1 (B7-H1, CD274) and PD-L2 (B7-DC, CD273) can promote tumor growth by preventing activation of cytotoxic T-cells." (PMID 37452307, 2023). "COL1A2 was positively correlated with CD274, CTLA-4, and PDCD1 based on TIMER data which was adjusted by tumor purity." (PMID 37805556, 2023). "HMTs have the capacity to inhibit the expression of PD-L1 by increasing H3K27me3 levels on the promoters of CD274 (PD-L1 gene), potentially reducing the immune evasion capabilities of tumor cells." (PMID 38077327, 2023). "Within the tumor microenvironment, immunecheckpoints such as theprogrammed cell death protein PD-1 (CD279) and its ligand programmeddeath ligand 1 (PD-L1) (CD274) play a crucial role in regulating theimmune response." (PMID 38038981, 2023). "The ligand of programmed death 1 (PD-1) (CD274 and PDCD1LG2) is the key mechanism leading to tumor immune escape." (PMID 37510310, 2023). "PD1 (PDCD1), PD-L1 (CD274), CTLA-4, and TIM-3 (HAVCR2) are important immune checkpoints responsible for tumor immune escape." (PMID 36714030, 2023). "PD-L1 is a transmembrane protein (also known as CD274 and B7-H1) that is primarily expressed on the cellular surface of antigen-presenting cells and tumor cells." (PMID 36430974, 2022). "PD-1, which binds to PD-L1, also known as CD274, or to PD-L2/CD273, is a peripheral immune checkpoint of immune, tumor, and stromal cells, whereas CTLA-4 binds to CD80/CD86, also known as B7-1/B7-2 co-stimulatory receptors, on antigen-presenting cells (APCs)." (PMID 35159208, 2022). "Then, we analyzed the correlation between SLC3A2 expression and 60 immune check-point genes, of which 24 were stimulatory, like ICOS and CD28, while the other 36 genes were inhibitory for anti-tumor immunity, such as PD1 and PDL1 (CD274)." (PMID 35992269, 2022). "We finally showed that non-responders to anti-PD-1 and/or anti-CTLA-4 ICI therapies have lower IFNG, Merck18, CD274 and CD8 scores, and lower dysfunction of the tumor." (PMID 36389735, 2022). "The results showed that CD276, CD40, CD274, CD44, and NRP1 expression was exclusively upregulated in cluster 0 (invasive tumor)." (PMID 36685583, 2022). "Previous studies have shown that infiltration of multiple immune cells, activation of CD274 (PD-L1), LAG3 and HAVCR2(TIM-3) and high immune scores played a crucial role in hot tumor." (PMID 35860239, 2022). "SIGLEC15, PDCD1LG2 (PD-L2), TIGIT, PDCD1 (PD-1), CD274 (PD-L1), CTLA4, LAG3, and HAVCR2 (TIM3) are transcripts related to immunological checkpoints that perform a vital function in tumor immune evasion." (PMID 36042287, 2022). "At the same time, our analysis found that PROZ was negatively correlated with genes related to immunotherapy efficacy such as CD8A, CD274 and GZMA, and was also negatively correlated with T-cell infiltration in tumor tissue." (PMID 36140703, 2022).
tumor (continued). "Among them, TGFB1 and VEGFA are tumor-secreted immunosuppressive factors, while CD274 (PDL1) and PDCD1LG2 are both PD1 ligands and cell-surface immunosuppressive factors." (PMID 35222383, 2022). "The interaction of CD274 (PDL1) and PDCD1 (PD1) suppresses the cellular immune response of an organism, thus allowing tumor cells to evade surveillance and clearance by the immune system." (PMID 36090045, 2022). "Expression analysis revealed that HPV integration disrupted gene expression, but the upregulation of CD274, PDCD1LG2, FOXA1, and TNFSF4 provided opportunities for tumor immunotherapy." (PMID 35392231, 2022). "PD-L1, also known as CD274, is a transmembrane checkpoint protein expressed on various types of immune and tumor cells." (PMID 36362062, 2022). "A similar approach was applied to dissect tumor-specific B cell proliferation networks involving PD1 (PDCD1), PDL1 (CD274), and CTLA4." (PMID 35804895, 2022). "The results indicated that CD274/PDCD1LG2 expression was positively correlated with stromal, immune, and ESTIMATE scores but negatively correlated with tumor purity." (PMID 36276934, 2022). "And its ligand, programmed death-ligand 1 (PD‐L1, or CD274), is mainly expressed on various tumor cells." (PMID 35619700, 2022). "Through immune checkpoint gene expression analysis, the expression of HM13 was found to exhibit a significant correlation with several tumor inhibitory genes, especially VEGFB, LAG3, CD274, and TGFB1." (PMID 36046831, 2022). "This is justified by unprecedented tumor regression and long-term survival benefit in patients upon immune checkpoint blockade (ICB) of PD-1 or its ligand PD-L1 (CD274, B7-H1)." (PMID 35493461, 2022). "On tumor cells, the interaction between programmed death 1 receptor (PD-1, PDCD1) and its ligand programmed death-ligand 1 (PD-L1, CD274) is a critical immunosuppressive mechanism in cancer." (PMID 36230513, 2022). "Broadly, non-responders (high TIDE score) had significantly lower IFNG, Merck18, CD274 (PD-L1), CD8 and ‘dysfunction of the tumor’ scores." (PMID 36389735, 2022). "SIGLEC15, PDCD1LG2(PD-L2), TIGIT, PDCD1(PD-1), CD274(PD-L1), CTLA4, LAG3, and HAVCR2(TIM3) are immunological checkpoints that perform a vital function in tumor immune evasion." (PMID 35840882, 2022). "PD-1 binding receptor PD-L1, known as CD274 and B7 homolog 1 (B7-H1), is not only expressed in T cells, B cells, macrophages, and dendritic cells (DCs), but also existed in tumor cells and tissues 36-39." (PMID 35414774, 2022). "Programmed death-ligand 1 (PD-L1), also known as B7 homolog 1 (B7-H1) or CD274, is a major obstacle to antitumor immunity because it confers resistance to tumor-reactive T cells when bound to its receptor PD-1 (CD279)." (PMID 36109513, 2022). "For example, it is known that IFN-γ, produced by tumour-infiltrating T cells, enhances the expression of immune checkpoint molecules such as PD-L1 (CD274, B7-H1), which in turn engage cognate receptors on effector T cells to promote exhaustion and apoptosis." (PMID 35017553, 2022). "We also found DC-STAMP expression had a correlation with PDCD1, CD274, CTLA-4, and TIGIT which were exhaustion markers of T cells and considered a dysfunction of anti-tumor immunity." (PMID 35571050, 2022). "Immune checkpoint-related genes, including cytotoxic T-lymphocyte associated protein 4 (CTLA4), programmed cell death-ligand 1 (CD274, PD-L1), and programmed cell death 1 (CD279, PDCD1, PD-1), play vital roles in regulating tumor immune escape." (PMID 36227151, 2022). "PDCD1, CD274, CTLA4, LAG3, TIGIT, and HAVCR2 are important immune checkpoints responsible for tumor immune escape." (PMID 35252356, 2022). "TGFBR1, PDCD1LG2, CD274, and TNFSF14 are involved in tumor immune evasion and are effective targets for tumor immunotherapy." (PMID 36371223, 2022).
tumor (continued). "Programmed cell death 1-ligand 1 (PD-L1), also known as B7-H1 or CD274, is one of the most critical immune inhibitory molecules in the TME and plays a vital role in tumor cell immune escape." (PMID 36071839, 2022). "Then, previous studies showed that BRD4 is another key mediator of both tumour cell constitutive and IFN‐γ‐stimulated CD274 transcription." (PMID 35083874, 2022). "Several signalling axes were shared by T cell subsets in the tumour microenvironment (for example, the ligands CD80, CD274 and PDCD1LG2, and the cytokines TGFβ1 and IL-15)." (PMID 35545675, 2022). "In 29 of 33 tumours, the expression of PTBP3 was positively correlated with the expression of immune checkpoint CD274." (PMID 35359851, 2022). "The interaction of the programmed death receptor ligands 1 and 2 (PDL1/CD274 and PDL2/CD273) on tumor cells with PD-1 receptors on T cells leads to reduced T-cell activation and proliferation, thus enabling tumors to evade immune response." (PMID 35740598, 2022). "Engagement of PD-1 with its ligand PD-L1 (or CD274), expressed on the surface of tumor cells and MDSCs, leads to the attenuation of TCR-mediated signaling." (PMID 35886899, 2022). "CD274 (PD-L1) and PDCD1LG2 (PD-L2) are involved in immunosuppression by tumor cells to evade cytotoxic T cell mediated killing and are associated predominantly with the EBV+ sub-type in a STAT1 driven manner as discussed later in this review." (PMID 35844493, 2022). "SIGLEC15, PDCD1LG2(PD-L2), TIGIT, PDCD1(PD-1), CD274(PD-L1), CTLA4, LAG3, and HAVCR2(TIM3) are transcripts related to immunological checkpoints that perform vital functions in tumor immune evasion." (PMID 36253777, 2022). "Programmed death ligand 1 (PD-L1, CD274), known as an essential immune checkpoint protein, is a crucial constituent of tumor immunosuppression that binds to programmed death 1 (PD-1) on T-cells." (PMID 34987636, 2022). "Programmed death-ligand 1 (PD-L1, synonyms: CD274 and B7-H1) is an immune checkpoint molecule expressed by tumor cells that can interact with programmed cell death protein 1 (PD-1, synonym: CD279), a receptor of T cells." (PMID 36013050, 2022). "This receptor is expressed mainly on activated T cells and, upon binding to its ligands PD-L1 (CD274) and PD-L2 (CD273) in tumor cells, transmits inhibitory signals to T cells, thereby helping to maintain a balance between immune tolerance and tissue damage." (PMID 35559250, 2022). "Finally, enrichment analysis confirmed that CD274 and PDCD1LG2 were associated with numerous biological pathways, such as: “Activation of Immune Reactions” and “Epithelial-Mesenchymal Transition,” suggesting that CD274 and PDCD1LG2 play crucial roles in cancer immunity and tumor metastasis." (PMID 36276934, 2022). "Additionally, the risk score was positively and significantly correlated with the expression levels of key ICB targets (i.e., CD274), indicating that high-risk HCC samples might be more affected by ICB pathways, thereby inhibiting anti-tumor immune activation and deteriorating prognosis accordingly." (PMID 35681134, 2022). "Immune checkpoint inhibitors (ICIs) enable the reversion of T cell suppression and enhance anti-tumor immune responses by blocking programmed cell death 1 (PD-1, PDCD1)/programmed death-ligand 1 (PD-L1, CD274) signaling." (PMID 35992797, 2022). "The expression level PD-L1, also called B7-H1 or CD274, is expressed in OS cells and immune cells, especially tumor-infiltrating lymphocytes (TILs)." (PMID 35884563, 2022). "To evaluate the effect of both compounds on genes/proteins previously demonstrated to be important in the tumor–macrophage interaction, we also evaluated the gene expression of CD274 (Pdcd1, PD-L1), TLR4, BMPR2 and miR-21 by RT-qPCR on the treated cell lines." (PMID 35053451, 2022).
tumor (continued). "Its ligand-programmed cell death protein ligand 1 (PD-L1, also known as CD274) is distributed not only on tumor cells and immune cells but also on other cells, such as vascular endothelial cells and pancreatic islet cells." (PMID 36497444, 2022). "PDL-1 (CD274), PD-1 (PDCD-1) and CTLA-4 were key immune checkpoints involved in tumor immune escape." (PMID 36248992, 2022). "The expression of CD274, CTLA4, LAG3, PDCD1, PDCD1LG2 and SIGLEC15 was significantly different between adjacent normal tissues and tumor tissues." (PMID 36588699, 2022). "Expressions of CD274, CTLA4, LAG3, PDCD1, PDCD1LG2, and SIGLEC15 were shown to be significantly different between normal and tumor samples in immune checkpoint analysis." (PMID 36588699, 2022). "CTLA4, HAVCR2, PVRL2, PDCD1, SIGLEC15, TIGIT, and VTCN1 expression levels were higher in tumor tissues, while CD244, LAG3, PDCD1LG2, and CD274 expression levels were found to be lower." (PMID 35923695, 2022). "CD274 (PD-L1) and PDCD1 (PD-1) are of great importance and play a crucial role in tumor immunosuppression and immunotherapy." (PMID 36552760, 2022). "The ligands of PD-1 are PD-L1 (CD274 or B7-H1) and PD-L2 (CD273 or B7-DC), which are typically expressed on the surface of APCs, tumor cells, and tumor-infiltrating lymphocytes (TILs) within the TME." (PMID 36311748, 2022). "PRMT5 inhibition not only decreased tumor cell survival but also increased the tumor cell expression of CD274 in vitro and in vivo, which activated the PD1/PD-L1 axis and eliminated CD8+T cell antitumor immunity." (PMID 35111150, 2021). "In our data, expression of PD-1 (PDCD1) was higher in CD8+ T cells in the tumor than in a normal lung, and PD-L1 (CD274) and PD-L2 (PDCD1LG2) were highly expressed in macrophages both from a normal lung and tumor." (PMID 33918618, 2021). "The main ligand of PD-1, programed death 1 ligand-1 (PD-L1), also known as B7 homolog 1 or CD274, is constitutively expressed or upregulated in various types of tumor cells." (PMID 35008669, 2021). "Given the rapid development of checkpoint inhibitor therapy across many tumor types, expression of immunoinhibitory molecules (e.g., CD274 or PD-L1) is of translational interest." (PMID 34818552, 2021). "In contrast to constitutive PD-L1 expression by tumor cells due to CD274 amplification, PD-L1 was induced in tumors and infiltrating immune cells in EBV (+) GC in response to adaptive immune resistance." (PMID 33479394, 2021). "To verify our guess, we investigated tumor-related immune checkpoints, including CD273, CD274, CTLA-4, and the ones that were newly emerging, LAG-3, TIM-3, TIGIT, CD276, BTLA, and IDO1, between the two subgroups." (PMID 33558879, 2021). "At 6 days from the tumor injection, human astrocytes are defined by JAK/STAT pathway activation, an increased expression of CD274+, IL-10, and IFNγ secretion." (PMID 33804873, 2021). "Programmed cell death protein 1 (PD-1/PDCD1), programmed cell death 1 ligand 1 (PD-L1/CD274), and cytotoxic T lymphocyte antigen 4 (CTLA-4) are vital immune checkpoints that play important roles in tumor immune escape." (PMID 34938665, 2021). "In response, tumor-reactive astrocytes increase expression of CD274 as well as IL-10 and IFN-γ by reprogramming myeloid cells and upregulating PD-L1 and FasL." (PMID 34949203, 2021). "More importantly, the expression level of CD274 and PDCD1LG2 was significantly correlated with the degree of Estimation of STromal and Immune cells in MAlignant Tumor tissues using the Expression data (ESTIMATE)." (PMID 33833994, 2021). "Through transducing negative signaling of effector T cell activity by the interaction with programmed death-ligand 1 (PD-L1, CD274), PD-1 serves as a mediator for tumor cells to survive by escaping T cell killing." (PMID 34172932, 2021).
tumor (continued). "Sarcoma data from the TCGA were downloaded to analyze the lncRNAs positively correlated with immune checkpoint inhibitory molecules (CD274, CD80, CD86, PDCD1 LG2 and LGALS9), which accelerate the process of tumor cell immune evasion." (PMID 34178688, 2021). "Each CD44+ cell-type functions immunosuppression through different ways: CD44+ tumor cells express CD276, IL13, VEGFA, and IDO1; CD44+ TAMs express IL10, TGFB1, VEGFA, and HAVCR2; CD44+ T cells express CD274, TGFB1, CTLA4, LAG3, and PDCD1." (PMID 35187044, 2021). "We also integrated the macrophage score with ERN1 and EIF2AK3 to predict CD274 expression in an ordinary least squares (OLS) linear regression model, including the tumor type as a covariate." (PMID 32520957, 2020). "Immune checkpoint molecule PD-1 (CD279) is primarily expressed on T cells, and PD-L1 (CD274) is primarily expressed on antigen-presenting cells (APC), immunosuppressive macrophages, and tumor cells." (PMID 33182298, 2020). "According to the image created by UCSC Xena, in the TCGA tumor samples, the DNA copy numbers of Siglec-15, SMAD7 and ATP5A1 showed a similar trend, while Siglec-15 and CD274 (PD-L1) showed the opposite trend." (PMID 32201516, 2020). "PD-L1 (CD274, also called B7-H1), one of the ligands of PD-1, is highly expressed on many tumor cells, antigen presenting cells, epithelial cells, parenchymal cells and virus infected cells." (PMID 33193386, 2020). "Based on survival data, we isolated F4/80 tumor-infiltrating macrophages of tumor-bearing Ern1-CKO mice to assess the UPR/IIS and Cd274 gene expression status." (PMID 32520957, 2020). "For example, checkpoint ligand-receptor pairs, such as tumor Treg CD80-Th17 cell CTLA4 and tumor Treg CD274-Th17 cell PDCD1, were identified in our study." (PMID 33584715, 2020). "IFN-γ neutralization reduces tumor-infiltrating PD-L1+ MDSCs in vivo, and mechanistically, IFN-γ upregulates IRF1, which in turn binds to IRF-binding sequence in cd274 promoter and activates PD-L1 expression." (PMID 32793192, 2020). "Programmed death ligand 1 (PD-L1), also called CD274, is the ligand of PD-1 expressed on immune cells, including antigen-presenting cells, and tumor cells." (PMID 33216754, 2020). "Based on the co-expression correlation between CD274 and CD8A in 29 tumor types, and between GZMA and PRF1 in 32 tumors, we further classified TME into eight groups according to IRGs’ expression level." (PMID 33585244, 2020). "Although cancer cells use myriad arsenal of immunosuppressive mechanisms to escape from the host immune system, PD-L1 (also known as CD274 or B7-H1), seems to be one of the hallmarks of a progressive tumour which can hamper (immuno)therapy efficacy." (PMID 32487171, 2020). "Programmed death-ligand 1 (PD-L1, B7-H1, or CD274) is present on the surface of dendritic cells or macrophages, but is also frequently over-expressed in tumor cells." (PMID 31214171, 2019). "Programmed cell death-ligand 1 (PD-L1), also known as cluster of differentiation 274 (CD274) or B7-H1, is one of the PD-1 ligands and is expressed in on tumor cells and immune cells." (PMID 31039792, 2019). "The results suggested a superior prognostic value of the CD274 (PDCD1 ligand 1, PD-L1) and PDCD1 in TNBC tumor immune microenvironment as compared to classical clinicopathological parameters." (PMID 35582587, 2019). "Binding of PD-1 with its ligands (PD-L1/L2; known as CD274 and CD273) transmits a co-inhibitory signal in activated T-cells that promotes T-cell exhaustion, leading to tumor immune evasion." (PMID 35582595, 2019). "It was suggested that tumor-related genes such as NNMT, FLI1, GAS6, IncRNA CCAT1, PDCD1LG2, and CD274 are key regulators in tumor-like transformation under long-time exposure to P. gingivalis." (PMID 30671195, 2019).